TEX35 (testis expressed 35)
Synonyms: C1orf49; DKFZP564J047; TSC24
Tractability: PROTAC: ubiquitination databases record sites on it.
Gene: Protein-coding gene on chromosome 1 (178,513,109 to 178,548,602, forward strand). Ensembl gene ENSG00000240021.
Gene Ontology:
Cellular component: microtubule cytoskeleton; nucleus
Genetic constraint (gnomAD): Loss-of-function variants: 16 observed, 25.28 expected, observed/expected ratio (o/e) 0.63, 90% interval 0.43 to 0.96. The upper end of that interval is the gene's LOEUF score, 0.96, which puts it in group 4 of 6, group 1 being the genes least tolerant of losing a copy. Missense variants: 184 observed, 194.21 expected, observed/expected ratio (o/e) 0.95, 90% interval 0.84 to 1.07. Synonymous variants: 56 observed, 64.69 expected, observed/expected ratio (o/e) 0.87, 90% interval 0.7 to 1.08.
Homologues: Orthologues: chimpanzee TEX35 (83% identical), macaque TEX35 (80% identical), dog TEX35 (66% identical), pig TEX35 (63% identical), guinea pig TEX35 (52% identical), mouse Tex35 (47% identical), rat Tex35 (46% identical).